XPC (XPC complex subunit, DNA damage recognition and repair factor)
Diseases named in the same sentence as XPC in open-access papers (continued):
Sharing a sentence is not in itself a finding about the gene and the disease.
lung carcinoma (continued). "Further larger studies with more comprehensively selected tagging SNPs in Chinese populations are needed to confirm our findings and some mechanistic studies are warranted to investigate the functions of XPC SNPs and mechanisms underlying their associations with lung cancer risk." (PMID 17498315, 2007). "Our results support that polymorphisms in two different NER genes (XPC and XPD) increased the risk of developing lung cancer, so individuals homozygous for the XPC PAT+, XPD 312Asn or XPD 751Gln alleles have a higher risk of developing lung cancer (ORs 1.28, 1.52 and 1.38, respectively)." (PMID 17705814, 2007). "Numerous studies associate various XPC SNP polymorphisms with lung cancer development, which, among other factors, may be influenced by gender and cigarette smoking status, and many XPC polymorphisms have been found to functionally modulate DNA repair capacity." (PMID 35530314, 2022). "Recently, two studies in Asian populations suggest that genetic polymorphisms in the XPC gene may be associated with risk of lung cancer, but these studies were either relatively small or the genotyping work did not take into account of all reported SNPs in the XPC gene." (PMID 17498315, 2007). "Furthermore, despite the fact that the polymorphism in XRCC3 didn't alter the overall risk of developing lung cancer when studied independently, when this polymorphism was combined with those studied in XPC or XPD, we observed an interaction between these polymorphisms." (PMID 17705814, 2007). "In cancer cells, XPC overexpression suppressed the proliferative and metastatic capacities of H446 lung cancer cells and abrogated the effects of circ_0004470 on promoting proliferation and metastasis." (PMID 40157540, 2025). "In contrast, lung cancer cells exhibit greater resilience to cigarette smoke, requiring higher doses to induce comparable DNA damage and apoptosis, and are less reliant on XPC expression for survival." (PMID 40060594, 2025). "The present study showed that circ_0004470 plays a role in the pathogenesis of lung cancer induced by BPDE via interactions with mRNAs or the XPC and DDB1 proteins." (PMID 40157540, 2025). "We found that XPC expression was significantly lower in the lungs and blood of lung cancer patients than in those of the controls." (PMID 40157540, 2025). "In this study, we also investigated the correlations between 35 polymorphisms in 9 DNA repair genes (XRCC3, BRCA2/ZAR1L, XPC, RAD52, MAD2L2, NFKB1, NFKBIA, TNFRSF1A, and FASN) with platinum-based chemotherapy prognosis in 399 patients with lung cancer." (PMID 35899106, 2022). "The strongest evidence supporting a critical role of XPC in lung cancer comes from translational animal studies." (PMID 35530314, 2022). "For instance, overexpression of ubiquitin ligases, such as Cullin-RING ubiquitin ligase 4 A (CUL4A), is common in cigarette smoke-related lung cancer, and inversely correlates to XPC expression." (PMID 35530314, 2022). "In the most common subset of lung cancers, non-small cell lung cancer (NSCLC), decreased tumor XPC mRNA level has been associated with poor outcomes." (PMID 35530314, 2022). "siXPC was used to knock down XPC in lung cancer cell lines to study the effect of XPC on the expression of lung cancer stem cell biomarkers and the ability of cell invasion." (PMID 34803670, 2021). "And shXPC was used to knockdown XPC in A549 and H1650 to study the effect of XPC on the expression of lung cancer stem cell biomarkers." (PMID 34803670, 2021). "This study aimed to study and analyze the correlation of XPC with lung cancer stem cell biomarkers expression and the overall survival (OS) of lung adenocarcinoma patients." (PMID 34803670, 2021). "Downregulation of XPC in lung cancer cells showed increased expression of cancer stem cell biomarkers and the increased cell invasion abilities." (PMID 34803670, 2021).
lung carcinoma (continued). "The overexpression of XPC reduced the cytotoxic effect of platinum-based chemotherapeutic drugs such as cisplatin and rendered lung cancer cells resistant to the platinum-based chemotherapeutic drugs." (PMID 34803670, 2021). "XPC also plays an important role in the lung cancer occurrence with the mechanism remian unclear up to date." (PMID 34803670, 2021). "The cell scratch experiment also further proved that the decrease of XPC expression resulted in increasing the migration of lung cancer cells." (PMID 34803670, 2021). "Flow cytometry and Western blotting proved that the decrease of XPC expression can significantly increase the expression of lung cancer stem cell markers." (PMID 34803670, 2021). "This suggesting that the decrease of XPC expression can lead to the recurrence of lung cancer by increasing the stemness of cancer cells." (PMID 34803670, 2021). "Tumor-bearing experiments found that the decreased expression of XPC can significantly promote tumor growth, which is closely related to the regulation of the stemness of lung cancer cells by XPC." (PMID 34803670, 2021). "Our previous study consistently showed an inverse correlation between CUL4A and XPC or P21 in lung carcinoma patients." (PMID 32587774, 2020). "Early studies identified associations with lung cancer risk in selected mutated NER genes (ERCC1-6, LIG1, POLE, XPA, and XPC genes)." (PMID 30181806, 2018). "Letkova and his colleagues investigated the polymorphisms of selected DNA repair genes, including XPC, XPD, hOGG1 and XRCC1, and found the different risks of developing lung cancer when stratified by gender, which further supporting our current findings." (PMID 26228655, 2015). "In the current study, both XPC and p27Kip1 was down regulated by eIF3a, which was in agreement with our previous finds in the lung cancer." (PMID 26213845, 2015). "We observed an increase of Snail expression at the mRNA and protein levels and a concomitant decrease of E-cadherin expression after knockdown of XPC in lung cancer cell lines." (PMID 25871391, 2015). "A lot of studies have shown that several polymorphisms of xeroderma pigmentosum complementation group C gene (XPC), a key enzyme in the NER pathway, are associated with impaired DNA repair capacity and susceptibility to lung cancer." (PMID 24736739, 2014). "This meta-analysis was performed to determine the relationship between XPC polymorphisms (Lys939Gln, Ala499Val, and PAT) and lung cancer risk." (PMID 24736739, 2014). "Attenuated XPC protein has been observed in many types of cancer, including bladder and lung cancer." (PMID 21507255, 2011). "The results obtained from others and our recent studies reveal reduced levels of XPC protein in the tumors for a majority of bladder and lung cancer patients." (PMID 21507255, 2011). "In conclusion, we analysed the association between XPC, XPD, XRCC1, and XRCC3 polymorphisms and the individual susceptibility to develop lung cancer in the Spanish population, specifically with a highly tobacco exposed population." (PMID 17705814, 2007). "There are only a few published studies that investigated the role of XPC SNPs in the etiology of lung cancer, mostly in Asian populations." (PMID 17498315, 2007). "Finally, in order to test whether individual polymorphisms in DNA repair genes might interact and modify the risk of developing lung cancer, ORs were estimated for each pair of the studied polymorphisms (XPC PAT, XPD Asp312Asn, XPD Lys751Gln, XRCC1 Arg399Gln and XRCC3 Thr241Met)." (PMID 17705814, 2007). "A recent study carried out in an Asiatic population of 432 cases and 432 controls was unable to find any association between the XPC PAT polymorphism and the risk of developing lung cancer." (PMID 17705814, 2007). "Given that both DDB2 and XPC are key components of NER machinery, we sought to determine whether the NER pathway is involved in KRAS mutation–driven platinum resistance in lung cancer." (PMID 39960727, 2025).
lung carcinoma (continued). "Moreover, qRT-PCR analyses showed that both the DDB2 and XPC genes were expressed at much higher levels in primary KRAS-mutant lung cancer cells compared with primary KRAS WT lung cancer cells." (PMID 39960727, 2025). "Although we did not investigate the underlying mechanism of decrease XPC mRNA, reductions in the 3p gene, where XPC is located, are common and occur early in lung cancer, which may account for this reduction." (PMID 40060594, 2025). "In addition, the m6A methylation levels of DDB2 and XPC transcripts were also higher in primary KRAS-mutant lung cancer cells compared with primary KRAS WT lung cancer cells." (PMID 39960727, 2025). "Our central hypothesis posits that decreased XPC mRNA expression in lung cancer cells leads to reduced DNA repair, increased DNA damage, and genomic instability, which ultimately contribute to lung cancer development." (PMID 40060594, 2025). "To determine whether circ_0004470 regulates the function of lung cancer cells through XPC, we performed cotransfection experiments." (PMID 40157540, 2025). "To test whether XPC can affect the migratory ability of lung cancer cells, we conducted a cell scratch experiment." (PMID 34803670, 2021). "In our study, XPC was knocked down with siXPC in lung cancer cells A549, H1299, and H1650." (PMID 34803670, 2021). "The relationship between XPC and lung cancer cell stemness is unclear." (PMID 34803670, 2021). "Nevertheless, we did not detect a significant association between XPC rs2228000 and other types of cancer, such as lung cancer, melanoma, pancreatic cancer, or colorectal cancer." (PMID 31710080, 2019). "Therefore, enhancing XPC expression in NSCLC cells with an epithelial phenotype would be a promising strategy to slow down the progression of lung cancer." (PMID 25871391, 2015). "While the XPC Gln939Gln genotype was associated with significantly increased risk of lung cancer in Asian population and in Caucasian population, the PAT −/− genotype significantly reduced lung cancer risk." (PMID 24736739, 2014). "However, the association between XPC polymorphisms (Lys939Gln, Ala499Val, and PAT) and lung cancer risk was still inconclusive and previous meta-analyses did not fully elucidate this issue." (PMID 24736739, 2014). "In fact, recently reported results suggest that DNA methylation may play an important role in XPC gene silencing of lung cancer cells." (PMID 21507255, 2011). "Individuals with the XPC PAT(+/+)/XRCC3 241Met/Met or XPD 751Gln/Gln/XRCC3 241Met/Met genotypes showed a not significant higher risk of developing lung cancer 3.06 (CI = 0.91–10.30) (P = 0.071) and 2.66 (CI = 0.74–9.62) (P = 0.135) respectively." (PMID 17705814, 2007). "Additionally, interaction between XPC and XPD polymorphisms showed an increased risk of lung cancer (OR = 2.25)." (PMID 17705814, 2007). "We investigated the relationship between polymorphisms in two NER genes, XPC (poly (AT) insertion/deletion: PAT-/+) and XPD (Asp312Asn and Lys751Gln), the BER gene XRCC1 (Arg399Gln), and the DSBR gene XRCC3 (Thr241Met) and the risk of developing lung cancer." (PMID 17705814, 2007). "Although the relative risks for individuals carrying the polymorphisms in XPC and XPD genes are modest (ORs < 1.52), these polymorphisms could account for a large proportion of lung cancers, as they are very common in the population." (PMID 17705814, 2007). "Moreover, several studies have carried out combined analysis between lung cancer risk and polymorphisms in different NER genes including XPC and XPD." (PMID 17705814, 2007). "We have previously shown that the PAT+ allele is in complete linkage disequilibrium with the intron 11 A-allele, reflecting the XPC haplotype (PAT+/939Gln/intron 11 A) with a reduced ability to repair DNA lesions and an increased risk of developing lung cancer." (PMID 17705814, 2007).
lung carcinoma (continued). "We have determined the frequency of 5 polymorphisms in 4 different genes implicated in DNA damage repair (XPC PAT, XPD Asp312Asn, XPD Lys751Gln, XRCC1 Arg399Gln, and XRCC3 Thr241Met) in lung cancer patients and matched controls in order to evaluate their association with the risk of lung cancer." (PMID 17705814, 2007). "However, the impact of XPC and inhaled cigarette smoke total lung and the lung microenvironment, known to be important in lung cancer development, may differ in vivo than that observed in these in vitro studies." (PMID 40060594, 2025). "We hypothesized that downregulation of XPC could increase the expression of lung cancer stem cell biomarkers and the cancer cell stemness, thereby affecting the occurrence of lung cancer and prognosis of lung cancer patients." (PMID 34803670, 2021). "The XPC Lys939Gln and Ala499Val polymorphisms occur in the protein coding regions and cause amino acids substitution in functional domain, thus it is reasonable that the functional polymorphisms of XPC (Lys939Gln, Ala499Val, and PAT) will alter DNA repair capacity and susceptibility to lung cancer." (PMID 24736739, 2014). "Furthermore, reduced XPC mRNA and protein levels were more frequently observed in both XP heterozygotes and lung cancer patients, suggesting that the amount of XPC may modulate susceptibility to cancer." (PMID 17498315, 2007). "XPC mRNA expression was also downregulated in NNK- and Cd-induced malignant cells and lung cancer cell lines (A549, H1299, and H446) and even lower in the lungs and blood of mice with high circ_0004470 expression." (PMID 40157540, 2025). "To explore the function of XPC as a tumor suppressor in lung cancer, we first down-regulated XPC expression in NSCLC cell line A549 by transient transfection with XPC siRNA, and analyzed the cell proliferation and migration in vitro." (PMID 25871391, 2015). "According to our genome-wide transcriptomic analysis and Q-PCR validation, we found that the DNA damage-related genes ERCC1, XPC, and CRY1 were up-regulated in hinokitiol-treated lung cancer cells." (PMID 25105411, 2014). "Our study suggests that cigarette smoke exposure leads to decreased XPC mRNA expression, exacerbates total and oxidative DNA damage, hinders NER, and may contribute to lung cancer development." (PMID 40060594, 2025). "Another novel finding is that decreased human XPC mRNA is not solely due to cigarette smoke exposure or field effects from lung cancer." (PMID 40391767, 2025). "Another novel finding is that the decrease in human XPC mRNA is not solely due to cigarette smoke exposure or field effects from lung cancer." (PMID 40060594, 2025). "In conclusion, our research shows that decreased expression of XPC can increase the expression of stem cell markers (CD133, OCT4), which in turn affects the proliferation and migration of lung cancer cells, then has an adverse prognosis for patients with lung adenocarcinoma." (PMID 34803670, 2021). "Importantly, XPC protects against chromosomal instability in benign bronchial epithelial cells, but not in lung cancer cells." (PMID 40060594, 2025). "In the present study, we found that two rSNPs (ERCC1 rs3212924 and XPC rs2229090) were associated with PFS and one rSNP (ERCC4 rs1799798) associated with OS of NSCLC patients, and these associations were not previously reported for lung cancer." (PMID 28878296, 2017).
breast carcinoma (23 papers, 2013 to 2025). "The XPC splice acceptor site variant, c.2251-1G > C, that was detected in two breast cancer patients (BRB114 & BRB161), is an ancient founder variant that is thought to have occurred ~ 800 years ago in the Bantu population of West-Central Africa52." (PMID 35039564, 2022). "The abnormal expression of the XPC protein is related to cancer progression, and the TT genotype seems to be associated with an increased risk of bladder and breast cancers." (PMID 35149893, 2022). "XPC polymorphisms are associated with higher susceptibility of breast cancer during the nucleotide excision repair (NER) process." (PMID 34207556, 2021). "Stratified analysis of menopausal status revealed that XPC rs2228000 has a higher breast cancer risk in the premenopausal sub-cohort." (PMID 27768589, 2016). "We found that carriers of the T allele of ERCC1 rs11615, XPC rs2228000 and rs50872, particularly in postmenopausal females, have an increased risk of breast cancer." (PMID 27768589, 2016). "An independent study reported that presence of the XPC rs2228000 T allele (CT or TT genotype) was associated with estrogen receptor positive breast cancer." (PMID 27768589, 2016). "In conclusion, our study deduced that ERCC1 rs11615 (CT or CT/TT), XPC rs2228000 (TT or CT/TT) and rs50872 (CT or CT/TT) were risk factors associated with increased breast cancer incidence, especially in postmenopausal women." (PMID 27768589, 2016). "In all, these studies suggest that patients harboring the XPC rs2228000 T allele have a higher risk of breast cancer." (PMID 27768589, 2016). "In general, the TT genotype of XPC rs2228000 may be linked to an increased risk of bladder and breast cancers, whereas the CT genotype is more likely to be associated with a reduced susceptibility to gastric cancer in the Chinese population." (PMID 31710080, 2019). "On the contrary, XPA rs1800975 and XPC rs2228001 were associated with decreased breast cancer risk." (PMID 27768589, 2016). "Besides, ERCC1 rs11615 (T allele), and ERCC2/XPD rs50872 (T allele) were associated with postmenopausal breast cancer, while XPC rs2228000 (T allele) was associated with premenopausal breast cancer." (PMID 27768589, 2016). "In addition, in the Asian population subgroup, XPC rs2228000 TT genotype was a risk factor for breast cancer." (PMID 27768589, 2016). "In addition, ERCC1 rs11615 carriers have a high risk of breast cancer with grade 3, while XPC rs2228000 and ERCC2/XPD rs50872 are linked to a high risk for breast cancer with grades 1 and 2, respectively." (PMID 27768589, 2016). "Pooled results suggested that XPC rs2228000 TT was associated with increased breast cancer risk." (PMID 27768589, 2016). "Similarly, in the population-based studies subgroup, XPC rs2228000 TT genotype was correlated with an increased risk of breast cancer." (PMID 27768589, 2016). "They hypothesized that genetic variation in the nucleotide excision repair pathway genes could modulate DNA repair capacity and contribute to breast cancer risk and found an association between RAD23B and breast cancer risk, and between XPC and RAD23B and DNA repair capacity in the cases." (PMID 30781715, 2019). "In breast cancer, the landscape of NER-related genetic mutations varies by races; increased risks of developing breast cancer in women are found to be correlated with different ERCC1, XPC, or XPD polymorphisms in postmenopausal Chinese and American women." (PMID 39334297, 2024). "In relation to DNA single-strand break repair genes, a case–control study in Puerto Rico tested associations between SNPs in the xeroderma pigmentosum (XPC and XPD) and ultraviolet (UV) excision repair protein (RAD23B) genes and breast cancer risk." (PMID 30781715, 2019). "The result showed that ERCC1 rs11615, XPC rs2228000, and ERCC2/XPD rs50872 carriers have a higher breast cancer risk in the whole study population." (PMID 27768589, 2016).